NES (nestin)
Diseases named in the same sentence as NES in open-access papers (continued):
Sharing a sentence is not in itself a finding about the gene and the disease.
cardiovascular disease (2 papers, 2018 to 2025). "eQTL analysis reveals an association between SNPs linked to cardiovascular disease and reduced aortic EC nestin mRNA expression." (PMID 30279450, 2018). "Further investigation of the CPC subpopulation (nestin+TBX5+SCA-1+) may enhance therapeutic strategies for cardiovascular diseases." (PMID 40869420, 2025).
CNS tumor (2 papers, 2008 to 2023). "Co-expression of nestin and CD133 was previously recognized to be a typical characteristic of CSCs in CNS tumors, but it was found also in other tumors of ectodermal origin." (PMID 18925963, 2008). "The neural stem cell markers SOX2 and Nestin were also either not differentially expressed or under-expressed in the PLAGL-amplified type compared to the other CNS tumor types." (PMID 36437415, 2023).
kidney diseases (2 papers, 2020 to 2022). "Further, nestin expression in podocytes is closely related to proteinuria in kidney diseases, and alterations of nestin may occur to enable podocytes to undergo morphological changes." (PMID 35149934, 2022).
bacterial infections (1 paper, 2022). "High expression of SPC24, NES, LOC116828075, CLSTN3, and PLAC8 was observed in the SPC24 cells of C. carbonaria, which were enriched in pathways involved in viral and bacterial infections, disease, and leukocyte transendothelial migration." (PMID 36552787, 2022).
epithelial neoplasm (1 paper, 2021). A benign or malignant neoplasm that arises from and is composed of epithelial cells. "Nestin is considered a CSC marker in epithelial neoplasms and has been shown to play key roles in differentiation, proliferation, migration, invasion, metastasis and survival of malignant neoplastic cells through regulation of the cytoskeleton and progenitor cells." (PMID 34201050, 2021).
retinopathy (1 paper, 2014). "In this study we assessed whether over-expression of Sirtuin1 in retinal neurons and vessels achieved by crossing Sirt1 over-expressing flox mice with Nestin-Cre mice or Tie2-Cre mice, respectively, may protect against retinopathy." (PMID 24416337, 2014).
NES also shares sentences with these, for which no sentence is quoted: gastrointestinal stromal tumor (4 papers); liver (3); small cell lung carcinoma (3); anaplastic astrocytoma (2); angiosarcoma (2); bladder urothelial carcinoma (2); chronic pancreatitis (2); colorectal adenocarcinoma (2); Creutzfeldt-Jakob disease (2); dystroglycanopathy (2); Glucose intolerance (2); Hyperinsulinemia (2); inflammatory bowel disease (2); lupus nephritis (2); nephrosis (2); oligoastrocytoma (2); pilocytic astrocytoma (2); pulmonary hypertension (2); soft tissue sarcoma (2); synovial sarcoma (2); type 2 diabetes (2); abortion (1); acute myocardial infarction (1); age (1); ameloblastic carcinoma (1); anaplastic oligoastrocytoma (1); anaplastic oligodendroglioma (1); aplastic anemia (1); brain disease (1); brainstem glioma (1).
A further 83 diseases each share a sentence with NES in 1 paper.